CD274 (CD274 molecule)
Diseases named in the same sentence as CD274 in open-access papers (continued):
Sharing a sentence is not in itself a finding about the gene and the disease.
cancer (continued). "Programmed death-ligand 1 (PD-L1), commonly referred to as CD274, is a protein located on the surface of specific cancer cells that helps control the immune system’s reaction to cancer." (PMID 37370832, 2023). "The interaction between CD274/PD-L1 and PDCD1/PD1 on T cells prevents cytotoxic T cell activation, allowing cancer cells to evade the immune system." (PMID 37675121, 2023). "TMB, in concert with CD274 (PD-L1) expression, serves as a biomarker panel for ICB selection in many kinds of cancers." (PMID 37251940, 2023). "PD1-related checkpoints were highly related to pyroptosis activities in different cancer types, including Programmed Cell Death 1 (PD-1, PDCD1), Programmed Cell Death 1 Ligand 1 (PD-L1, CD274), and Programmed Cell Death 1 Ligand 2 (PDCD1LG2)." (PMID 37863886, 2023). "We analyzed the expression profile of COMMD2 gene and ICGs (CD274, CTLA4, HAVCR2, LAG3, PDCD1, PDCD1LG2, SIGLEC15, and TIGIT) at a pan‐cancer level." (PMID 36205192, 2023). "A recent study shows the significant power of a model combining gene expression of immune-related genes, including CD274 and PDCD1, and the TMB to identify pan-cancer ICI-treated patients that will have a longer PFS and OS39." (PMID 37430006, 2023). "In most cancer types, CD274 (PD-L1), NRP1, and TNFSF15 were positively correlated with YAP1 expression." (PMID 36479120, 2022). "PDL-1 (CD274)/PD1 (CD279) is an important modulatory/inhibitory immune checkpoint mechanism, utilized by some cancers to target and suppress the adaptive immune response." (PMID 36552005, 2022). "The results indicated that strong positive relationships with PD-L1(CD274) and IRAK1 gene expression in diverse cancer types of TCGA." (PMID 35669566, 2022). "The expression of immune checkpoint (ICP) genes, such as PDCD1 (PD1), CD274 (PDL1), CTLA4, LAG3, and HAVCR2 (TIM3) has been utilized in predicting the response of patients to immune checkpoints therapy in a variety of cancers including PAAD." (PMID 35601487, 2022). "CTLA-4, PD1 (PDCD1), and PD-L1 (CD274) are targets of immunotherapy, and immune checkpoint blocking of these sites has revolutionized the paradigm of cancer therapy." (PMID 35771229, 2022). "Overexpression of four top candidate genes (CD274 (PD-L1), MCL1, JUNB, and B3GNT2) conferred resistance in diverse cancer cell types and mouse xenografts." (PMID 35338135, 2022). "The high CTL group had higher PD-L1 (CD274) expression than the low CTL group, which was common in all cancer types." (PMID 35525921, 2022). "For example, LAMP2 gene expression levels were positively correlated with those of immunoinhibitors CD274 (PD-L1) and CSF1R in a variety of cancers." (PMID 35530327, 2022). "In summary, our integrated analysis suggests that CD274 and PDCD1LG2 are suitable biomarkers for pan-cancer diagnostics." (PMID 36276934, 2022). "Correlation analysis of FDX1 with checkpoint gene expression found a high correlation (p < 0.05) with tumor necrosis factor (TNF)–related immune genes (TNFRSF14, 15, 25) and CTLA4, PDCD1, CD274, NRP1, and VTCN1 in some kinds of cancers." (PMID 36061184, 2022). "RALA was significantly correlated with the infiltration of B cells and macrophages, as well as the expression of immune checkpoint molecules such as CD274, CTLA4, HAVCR2 and LAG3, suggesting that RALA can be used as a kind of new pan-cancer immune marker." (PMID 36466919, 2022). "Programmed death ligand 1 (PD-L1, CD274) is a major co-suppressive checkpoint signal regulating immune escape in cancer patients." (PMID 36568423, 2022). "Due to recent advances in cancer therapy, immune checkpoint inhibitors (ICIs) are new classes of drugs targeting programmed cell death protein 1-ligand 1 (PD-L1, synonym CD274, B7) homolog 1) or its receptor (PD-1, synonym CD 279)." (PMID 35755033, 2022). "In particular, interactions between cytotoxic T lymphocytes (CTLs) and cancer cells, such as PD-1 (PDCD1) binding PD-L1 (CD274), are crucial for cancer cell clearance." (PMID 35651625, 2022).
cancer (continued). "Materials and Methods: Differences in expression levels of CD274 and PDCD1LG2 were analyzed in diverse cancer types using The Cancer Genome Atlas (TCGA) and Genotype-Tissue Expression (GTEx) databases." (PMID 36276934, 2022). "PD-L1, also known as B7-H1 or CD274, plays a part in inhibiting cancer-immunity cycle through binding to negative regulators of T-cell activation such as PD-1 and B7.1 (CD80)." (PMID 35621637, 2022). "In cancer cells BRD4 inhibition suppresses super-enhancer and IFN-γ driven transcription of PD-L1 (CD274 gene) by preventing binding of BRD4 and IRF1 to its promoter and enhancer regions." (PMID 36139513, 2022). "The excellent extrapolation of this generalized model to other cancer types for which fewer data are available provides confidence that the TFs IRF1, STAT1, NFKB, and BRD4 are in general dominant regulators of CD274 expression." (PMID 35289334, 2022). "We further explored the potential relationship between PD-L1 (CD274) and IRAK1 gene expression in diverse cancer types of TCGA." (PMID 35669566, 2022). "Among the upregulated immune checkpoint molecules, CD274, much more known as PD-L1, and CD276 were members of the B7 superfamily, through which cancer cells exhibit immune escape." (PMID 36467089, 2022). "Afterward, we evaluated the link between DTYMK expression and key immune checkpoints (CD274, CTLA-4, HAVCR2, LAG3, PDCD1, PDCD1LG2, SIGLEC15, and TIGIT) expression levels in pan-cancer." (PMID 36094557, 2022). "The key immune checkpoints (CD274, CTLA-4, HAVCR2, LAG3, PDCD1, PDCD1LG2, SIGLEC15, and TIGIT) also had a significant relationship with DTYMK expression in approximately 20 kinds of cancers, except in MESO, PCPG, and UCS." (PMID 36094557, 2022). "Here, we evaluated the correlation between three classic ICGs, CD274, CTLA4 and PDCD1, and MCM2 expression in 40 TCGA cancers." (PMID 35693940, 2022). "As most information is available for microRNAs targeting PD-L1 (CD274), we compared these results with those generated using MIO for different cancer entities (Use Case S1)." (PMID 35642895, 2022). "The TCGA and GTEx databases declared variable CD274 and PDCD1LG2 expression levels across 33 cancer types." (PMID 36276934, 2022). "MTHFD2 was overexpressed in various cancer cells and further elevated by IFN-γ, enhancing PD-L1(CD274) production at basal and IFN-induced levels." (PMID 35693982, 2022). "ICIs mainly represented by PD-L1 (CD274) have shown great value in researching and treating various malignant tumors." (PMID 35281840, 2022). "Generally, XIST expression was positively related to about half of these markers in various cancers, such as CD2000, CD200R1, CD274, members of the tumor necrosis factor (TNF) ligand family, and so on." (PMID 36212008, 2022). "Programmed death-1 receptor PD-1(CD279) and its corresponding ligands PD-L1(CD274, B7-H1) and PD-L2(CD273, B7-DC) play important roles in physiological immune tolerance and for immune escape in cancer disease." (PMID 36289665, 2022). "We also assessed the correlations between DAAM2 and the expression of immune checkpoints, including TIGIT, CTLA4, CD274, and PDCD1, across cancers." (PMID 35281277, 2022). "Taken together, the available research indicated that FOXP3, IRF3, CD274, and TP63 play an essential role in cancer, even in GBM." (PMID 35401877, 2022). "As CD274/PDCD1LG2 levels were found related with the clinical characteristics of LGG and SKCM, GO, KEGG analysis, and GSEA were performed for these two cancers." (PMID 36276934, 2022). "Owing to their immunosuppressive function, CD274 and PDCD1LG2 levels were found to be positively correlated with most immunosuppressive molecules across cancers, and both had a significant correlation with TGCT." (PMID 36276934, 2022). "PDCD1, CD274, CTLA4, LAG3, C10orf54, and BTLA expression had positive correlations in most cancer types, and in approximately half of the cancer types, GBP1 expression is positively correlated with CD276 expression." (PMID 35222540, 2022).
cancer (continued). "Assessment of genes most upregulated within NHS–rmIL-12–treated carcinoma revealed increased expression of IFN-γ–responsive genes involved in antigen presentation, including B2m, H2-A, Cd74, the immune checkpoint Cd274, and the T lymphocyte chemokine Cxcl9." (PMID 35260537, 2022). "TIGIT expression mediated infiltrated immune cells and positively correlated with the expression of LAG3, CTLA4, PDCD1 (PD-1), CD274 (PD-L1), PDCD1LG2 (PD-L2) in most of the cancer types." (PMID 34795387, 2021). "Similar to the striking differences observed with the CD274-correlated genes, there are again some differences with the PDCD1-correlated genes that are immediately apparent between cancers." (PMID 34067485, 2021). "In our cancer center patients with LIHC, the median serum CD274 and PDCD1LG2 level were 5.1 and 14.7 μg/μl, respectively." (PMID 33833994, 2021). "CD274 and PDCD1LG2 displayed inconsistent gene expression levels among the diverse cancer cell lines." (PMID 33833994, 2021). "We found in this study that the CD274/PDCD1LG2 expression was correlated with TMB and MSI in some cancer types." (PMID 33833994, 2021). "PD-L1(CD274) is a well-known immunosuppressive molecule, which confers immunoescape features to cancer cells and has become one of the major targets in cancer immunotherapies." (PMID 34741014, 2021). "Thirdly, we observed an increased expression of several immune checkpoints, including PD-L1 (CD274), PD-L2 (PDCD1LG2), CD73 (NT5E), and galectin-3 (LGALS3) in the nutlin-3 resistant cancer cells." (PMID 35582010, 2021). "The expression of immune checkpoint genes [e.g., PDCD1 (PD1), CD274 (PDL1), CTLA4, LAG3, and HAVCR2 (TIM3)] has been utilized in predicting the response of patients to ICB therapy in a variety of cancers including CC." (PMID 34733790, 2021). "It was found that most cancer types showed a CD274/PDCD1LG2 alteration frequency, and the abnormal expression served as a prognostic factor in some cancer types." (PMID 33833994, 2021). "An analysis between CD274/PDCD1LG2 and a methylase inhibitor is expected to inject a new vitality into the cancer treatment." (PMID 33833994, 2021). "While CD274 mRNA and protein expression may not accurately correlate with each other, observations of promoter hypomethylation being associated with CD274 overexpression in cancer are especially interesting from the scientific and clinical points of view." (PMID 34680073, 2021). "We found that the expression level of GRWD1 was positively correlated with the expression levels of immune checkpoint-related genes (CD274, CTLA4, HAVCR2, LAG3, PDCD1, PDCD1LG2, SIGLEC15, and TIGIT) in most types of cancer, especially in STAD." (PMID 34616846, 2021). "According to the results of CCLE analysis, CD274 and PDCD1LG2 showed inconsistent gene expression levels among the diverse cancer cell lines (p = 6.1e-20 and 6.9e-20), where pancreas cells had a relatively higher gene expression." (PMID 33833994, 2021). "First, we classified the immune phenotypes based on CD274 and TMB, which served as a strong predictor for patients with cancers treated with ICIs." (PMID 34100771, 2021). "PD1 engages a specific set of ligands, either PD-L1 (also known as CD274 and B7-DC) or PD-L2 (also known as CD273 and B7-DC), which are expressed on a variety of cell types including cancer cells." (PMID 34068491, 2021). "One of the best characterized immune checkpoints, and one of two unequivocally shown to operate in cancer cells, involves the interaction between programmed cell death-1 (PDCD1, often known as PD1) on the T cell and its ligand (CD274, often known as PD-L1)." (PMID 33578919, 2021). "PD-1 is more extensively expressed on activated cells than CTLA-4 and predominantly modulates effector CTL responses upon interaction with its ligand, programmed death-ligand 1 (PD-L1; B7-H1; CD274) and/or PD-L2 (B7-DC; CD273) on cancer cells." (PMID 33808294, 2021).
cancer (continued). "TIGIT expression also positively correlated with CTLA4, PDCD1 (PD-1), CD274 (PD-L1), ICOS in most of the cancer types." (PMID 34795387, 2021). "The difference in clinical relevance of CD274 and PDCD1 points to the unique molecular biology of each individual cancer type and highlights a need to identify where the differences lie." (PMID 34067485, 2021). "Programmed death 1 (PD-1) and its ligands, programmed death ligand 1 (PD-L1, or CD274) and PD-L2 (PDCD1LG2), are known as an immune checkpoint axis available to the cancer cells escaping from the immune destruction of T cells." (PMID 33833994, 2021). "PD-L1 (CD274) and CTLA4 are two well-studied immune checkpoints targeted for the treatment of patients with cancer." (PMID 33479597, 2020). "Generally, PRDM1 expression positively correlates with the expression of LAG3, CTLA4, PDCD1 (PD-1), CD274 (PD-L1), PDCD1LG2 (PD-L2), TIGIT in the majority of 33 cancer types." (PMID 33384601, 2020). "Recent studies have suggested that immune checkpoints play an important role in the immune escape of cancer, so we further analysed the relationship between the 4 subtypes and 8 immune checkpoint genes (PDCD1, CD274, PDCD1LG2, CTLA4, CD86, CD80 and CD267)." (PMID 31995855, 2020). "CD274 (PD-L1) is an adaptive immune response suppressor and blockade of PD1/PD-L1 represents a major cancer treatment breakthrough." (PMID 32923394, 2020). "PD1 expression is often upregulated in the TME, while its ligands, including PDL1 (CD274, B7-H1) and PDL2 (CD273, B7-DC), are upregulated in activated leukocytes and myeloid cells as well as in many cancer cells." (PMID 32944390, 2020). "PRDM1 expression positively correlates with the expression of LAG3, CTLA4, PDCD1 (PD-1), CD274 (PD-L1), PDCD1LG2 (PD-L2), TIGIT in the majority of 33 cancer types." (PMID 33384601, 2020). "PD-L1 (Programmed Death Ligand-1 receptor) or CD274 is expressed on the surface of certain activated immune components, such as B cells, T cells and NK cells CD14+-TAMs, and on the surface of cancer cells." (PMID 32183342, 2020). "PD-L1 (B7-H1, CD274) and PD-L2 (PDCD1LG2, B7-DC, CD273) are immune co-signaling molecules belonging to the B7 family, and they are expressed in several cancer types and, also, in infiltrating immune cells." (PMID 33194598, 2020). "In general, PD-L1 (programmed death-ligand 1; CD274) is expressed on the surface of cancer cells but only rarely expressed by normal tissues." (PMID 33383713, 2020). "Cancer immunotherapy based on blocking immune check-point molecules such as programmed cell death protein 1 (PD-1 or CD279) and its ligand 1 (PD-L1 or CD274 or B7-H1) is a popular topic under intensive investigation." (PMID 30770752, 2019). "An immune checkpoint blockade targeting the PD-1: PD-L1 (B7-H1; CD274) axis has revolutionized contemporary treatment for a variety of cancers." (PMID 30987269, 2019). "Targeting immune checkpoints, such as programmed cell death-1 (PD-1) and its ligand programmed death ligand-1 (PD-L1, also known as CD274 or B7-H1) has revolutionized the treatment of patients with cancer." (PMID 30564891, 2019). "More importantly, they were resistant to cisplatin, oxaliplatin and cyclophosphamide exhibiting high cross-resistance along with alterations in expression of cancer-stem cell markers such as CD133, CD166, CD24, CD26, CXCR4, CD271 and CD274." (PMID 30143021, 2018). "The scatter plot shows the relationship between the Th1 and Th2 scores and expression values of the three genes (CD274 (PD-L1), PDCD1LG2 (PD-L2), and PDCD1 (PD-1)) that were considered as cancer immunotherapy genes involved in the PD-L1/PD-1 axis." (PMID 29721184, 2018). "Similar to the whole population with all stages of cancer, patients with low-CD8A expression and high-CD274 expression had a poorer prognosis." (PMID 30318514, 2018).
cancer (continued). "PD-L1 (B7-H1, CD274) is the ligand for Programmed death-1 (PD-1, CD279) and is expressed on the surface of cancer cells in addition to its expression on infiltrating immune cells." (PMID 28881675, 2017). "Programmed death ligand-1 (PD-L1, also called B7-H1 or CD274), which is expressed on various cancer and immune cells, plays a crucial role in developing cancer immunoresistance by binding programmed death-1 (PD-1) on T-lymphocytes." (PMID 26822379, 2016). "Programmed death-ligand 1 (PDL1 or CD274), one of the ligands of PD1, is expressed at the surface of many cancer and immune cells such as antigen-presenting cells." (PMID 25940795, 2015). "In some cases, several genes (e.g., CD274 and NDUFC2) were amplified in two or more datasets that originated from a single cancer subtype." (PMID 24874471, 2014). "Other members of the B7 family include B7-H1 (PD-L1 or CD274), B7-DC (PD-L2), ICOS-L, B7-H3 and B7-H4, but only B7-H1 and B7-H4 have been indisputably shown to play a role in the immunoevasion of cancer cells." (PMID 21884581, 2011). "Notably, in cancers such as COAD, BRCA, LUAD, READ, and CESC, tumors in the low-succinylation group exhibited elevated expression levels of PDCD1 (PD-1), CD274 (PD-L1), and CTLA4 at both the transcriptional and protein levels." (PMID 40463370, 2025). "Finally, we sought to confirm that INCR1 regulates components of the IFNγ-induced JAK/STAT pathway and the resulting expression of immune checkpoints IDO1, CD274, and PDCD1LG2 in human LUAD cells, as shown in other cancer types." (PMID 40449595, 2025). "In addition, AURKA expression was significantly and positively correlated with immune checkpoint targets such as CD274, LAG3, and CTLA4 in most cancer types." (PMID 40718709, 2025). "Furthermore, in pan-cancer, TRPM6 was negatively correlated with CD274, LAG3, PDCD1, and SIGLEC15, and showed significant differences (P < 0.01)." (PMID 41562086, 2025). "ADM was found to exhibit a strong and consistent positive correlation with several immune checkpoint genes, including CD274 (PD-L1), CD276, TNFRSF18, TNFSF9, and PVR in the pan-cancer analysis, which contributed to the development of a suppressive immune microenvironment." (PMID 40529377, 2025). "Strong and consistent positive correlations were witnessed between ADM and several immune checkpoint genes, including CD274 (PD-L1), CD276, TNFRSF18, TNFSF9, and PVR in pan-cancer analysis, indicating its role in the development of suppressive immune microenvironment and T cell exhaustion." (PMID 40529377, 2025). "However, it was noteworthy that among these immune-related genes, CD274, CD276, TNFRSF18, TNFSF9, and PVR displayed strong correlations with ADM expression across almost all cancer types." (PMID 40529377, 2025). "Notably, genes such as HAVCR2, PDCD1LG2, CD274, and TIGIT exhibited the strongest positive correlations with STX7 across more than 20 cancer types, suggesting a role for STX7 in immune checkpoint-mediated regulation." (PMID 40999361, 2025). "Notably, cancer incidence increases with aging, which is accompanied by increased expression of PDCD and CD274." (PMID 38752723, 2024). "Single-cell RNA-seq analysis of a primary BC sample, focusing on examining the expression patterns of CD47, CD24, CD274, SIRPα and Siglec-10 at the individual cell level, revealed a prominent expression of CD47 and CD24 in cancer cells, notably higher than that of CD274." (PMID 38971872, 2024). "Different from what was seen in mouse dendritic cells, CD274 transcripts were not negatively correlated with IRF2 mRNA but rather had a positive correlation in some cancers." (PMID 39354629, 2024).